FAP (fibroblast activation protein alpha)
Description:
Cell surface glycoprotein serine protease that participates in extracellular matrix degradation and involved in many cellular processes including tissue remodeling, fibrosis, wound healing, inflammation and tumor growth. Both plasma membrane and soluble forms exhibit post-proline cleaving endopeptidase activity, with a marked preference for Ala/Ser-Gly-Pro-Ser/Asn/Ala consensus sequences, on substrate such as alpha-2-antiplasmin SERPINF2 and SPRY2. Degrade also gelatin, heat-denatured type I collagen, but not native collagen type I and IV, vitronectin, tenascin, laminin, fibronectin, fibrin or casein. Also has dipeptidyl peptidase activity, exhibiting the ability to hydrolyze the prolyl bond two residues from the N-terminus of synthetic dipeptide substrates provided that the penultimate residue is proline, with a preference for Ala-Pro, Ile-Pro, Gly-Pro, Arg-Pro and Pro-Pro. Natural neuropeptide hormones for dipeptidyl peptidase are the neuropeptide Y (NPY), peptide YY (PYY), substance P (TAC1) and brain natriuretic peptide 32 (NPPB). The plasma membrane form, in association with either DPP4, PLAUR or integrins, is involved in the pericellular proteolysis of the extracellular matrix (ECM), and hence promotes cell adhesion, migration and invasion through the ECM. Plays a role in tissue remodeling during development and wound healing. Participates in the cell invasiveness towards the ECM in malignant melanoma cancers. Enhances tumor growth progression by increasing angiogenesis, collagen fiber degradation and apoptosis and by reducing antitumor response of the immune system. Promotes glioma cell invasion through the brain parenchyma by degrading the proteoglycan brevican. Acts as a tumor suppressor in melanocytic cells through regulation of cell proliferation and survival in a serine protease activity-independent manner.
Synonyms: FAPalpha; SIMP; DPPIV; FAPA
Tractability: Small molecule: a structure with a bound ligand is known; a high-quality ligand is known; it has a high-quality binding pocket; it belongs to a druggable protein family. Antibody: a drug acting on it is in phase 2 or 3 trials; UniProt places it where antibodies can reach, with high confidence; its Gene Ontology location is reachable by antibodies, with high confidence; UniProt predicts a signal peptide or a membrane-spanning region. PROTAC: ubiquitination databases record sites on it; a small molecule that binds it is known. Other modalities: a drug acting on it is in phase 2 or 3 trials.
Target class: Enzyme; Serine protease SC clan; Protease; Serine protease S9B subfamily; Serine protease
Gene: Protein-coding gene on chromosome 2 (162,170,684 to 162,245,151, reverse strand). Ensembl gene ENSG00000078098.
Subcellular location: Cell surface (Prolyl endopeptidase FAP); Cell membrane; Cell projection, lamellipodium membrane; Cell projection, invadopodium membrane; Cell projection, ruffle membrane; Membrane; Secreted (Antiplasmin-cleaving enzyme FAP, soluble form); Cytoplasm (Isoform 2)
Gene Ontology:
Molecular function: dipeptidyl-peptidase activity; endopeptidase activity; identical protein binding; integrin binding; peptidase activity; protease binding; protein binding; protein homodimerization activity; serine-type endopeptidase activity; serine-type peptidase activity
Biological process: endothelial cell migration; negative regulation of extracellular matrix disassembly; negative regulation of extracellular matrix organization; protein catabolic process; proteolysis; regulation of collagen catabolic process; melanocyte apoptotic process; melanocyte proliferation; negative regulation of cell proliferation involved in contact inhibition; positive regulation of execution phase of apoptosis; regulation of cell cycle; regulation of fibrinolysis
Cellular component: cell surface; extracellular region; focal adhesion; lamellipodium; membrane; peptidase complex; plasma membrane; cytoplasm; ruffle membrane; apical part of cell; basal part of cell; lamellipodium membrane
Genetic constraint (gnomAD): Loss-of-function variants: 34 observed, 50.76 expected, observed/expected ratio (o/e) 0.67, 90% interval 0.51 to 0.89. The upper end of that interval is the gene's LOEUF score, 0.89, which puts it in group 3 of 6, group 1 being the genes least tolerant of losing a copy. Missense variants: 483 observed, 489.81 expected, observed/expected ratio (o/e) 0.99, 90% interval 0.91 to 1.06. Synonymous variants: 190 observed, 169.21 expected, observed/expected ratio (o/e) 1.12, 90% interval 1 to 1.27.
Homologues: Orthologues: chimpanzee FAP (100% identical), macaque FAP (99% identical), rabbit FAP (94% identical), dog FAP (93% identical), pig FAP (93% identical), mouse Fap (90% identical), rat Fap (89% identical), guinea pig FAP (86% identical), Caenorhabditis elegans dpf-2 (29% identical). Paralogues in human: DPP4 (52% identical), DPP10 (33% identical), DPP6 (32% identical), DPP8 (24% identical), DPP9 (22% identical), APEH (14% identical).
Diseases named in the same sentence as FAP in open-access papers:
FAP is named in the same sentence as 376 diseases in open-access papers, as found by Europe PMC text mining. Sharing a sentence is not in itself a finding about the gene and the disease. The quoted sentences say what the papers report.
breast carcinoma (183 papers, 2006 to 2026). "Recent studies highlight that the overexpression of FAP in the stomach, colorectal, and breast cancer was associated with tumor growth and metastasis." (PMID 39055892, 2024). "Although heterogeneity of FAP+ Cancer-Associated Fibroblasts (CAF) has been described in breast cancer, their plasticity and spatial distribution remain poorly understood." (PMID 38561380, 2024). "In primary pulmonary adenocarcinomas and in the metastasis of mammary carcinoma, cancer-associated fibroblasts were strongly FAP-positive." (PMID 39188902, 2024). "Upregulated FAP in breast cancer has been linked to advanced disease, older patients, lymph node metastases, as well as greater mortality rates." (PMID 37752545, 2023). "As a type II transmembrane serine protease, fibroblast activation protein (FAP) is specifically expressed on the surface of fibroblasts associated with a variety of epithelial-derived malignancies such as pancreatic cancer, breast cancer, and colon cancer." (PMID 36838669, 2023). "For example, the increase of α-SMA labeled CAFs cells in breast cancer is significantly associated with poor prognosis, and FAP+ CAFs are abundant in invasive breast cancer tumor tissue." (PMID 36152055, 2022). "CAFs with a high expression of FAP, αSMA, and PDGFRβ were found to have immunosuppressive properties and are thus presumably associated with more aggressive breast cancer phenotypes, such as triple-negative cancers." (PMID 33806802, 2021). "Recent studies show that the loss of HIF‐1αin FAP positive fibroblasts can reduce the vascular density and myeloid cell infiltration to promote the tumour perfusion in breast cancer model." (PMID 33943003, 2021). "Here, the authors show that in breast cancer models an IL-6 driven co-expression of FAP and HO-1 in tumour-associated macrophages, similar to the wound healing response, facilitates migration and metastatic spread." (PMID 30054470, 2018). "In the context of tumors, where fibroblasts may be tumor-promoting FAP+ Cancer-Associated Fibroblasts, Th2 cells contribute to pro-tumoral inflammation in pancreatic and breast cancers." (PMID 27177227, 2016). "FAP-α in significantly associated with poor outcome in patients with breast cancer." (PMID 24885257, 2014). "Furthermore, increased stromal expression of FAP-α is shown to be associated with longer survival of breast cancer patients." (PMID 24885257, 2014). "More work in a larger patient population is needed to dissect the role of FAP in various histopathologic variants and hormone-receptor status within the tumor microenvironment and explore its role as a potentially targetable molecule in breast cancer treatment." (PMID 37111277, 2023). "Although FAP-targeting molecular imaging enables precise tumor visualization, its application for microenvironment-responsive detection of breast cancer metastases remains unexplored." (PMID 42006731, 2026). "The results showed that HNav-FAP targeted and induced apoptotic cell death by activation of the mitochondria pathway in FAP+ breast cancer cells." (PMID 41328341, 2026). "In mouse models of breast cancer and melanoma, FAP antibody‐conjugated immunotoxins have exhibited robust antitumor efficacy." (PMID 40656546, 2025). "The high density of stromal components and the abundant presence of CAFs in breast cancer, along with the stable expression of FAP, are likely key factors contributing to the excellent imaging performance of FAPI PET in this tumor type." (PMID 40656546, 2025). "FAP-targeted CAR-T cells treat HER2-positive breast cancers and improve TNBC’s anticancer effect by removing CAFs." (PMID 39755633, 2025). "By eliminating CAFs, FAP-targeted CAR-T cells enhance the anticancer effect in TNBC in addition to treating HER2-positive breast cancers." (PMID 39755633, 2025). "The two developed NIRF agentswere characterized optically, in vitro on FAP-expressingcells and in vivo in an unexplored FAP-expressingpreclinical tumor model of breast cancer." (PMID 39954291, 2025).
breast carcinoma (continued). "Previous studies have shown intermediate expression of fibroblast activation protein (FAP) in ovarian and cervical cancers, along with high expression levels in breast cancer." (PMID 40022239, 2025). "DNA vaccines expressing FAPα successfully reduced tumor growth in the 4T1 breast cancer model by stimulating FAPα-specific CTL responses." (PMID 40890855, 2025). "This work aimed todevelop two novel NIRF imaging probes targeting fibroblast activationprotein FAP for breast cancer management." (PMID 39954291, 2025). "Other examples include sodium-fluoride PET in breast cancer spinal metastases, and fibroblast activation protein (FAP)-targeted radiotracers such as gallium-68 labeled FAP inhibitors ([68 Ga]Ga-FAPI) in bone metastases from lung cancer." (PMID 39470945, 2025). "Other cancers, including lung and breast cancers, have also shown positive responses to FAP‐based TRT, with some patients experiencing significant disease control and reduced metastasis." (PMID 40656546, 2025). "FAP-based vaccines are being developed to treat tumors by targeting CAFs, showing promising results in breast cancer." (PMID 40230452, 2025). "In a 4T1 breast cancer mouse model, the combination of stereotactic ablative radiotherapy and a cancer vaccine targeting fibroblast-activating protein-alpha (FAP-α) effectively suppressed metastatic growth." (PMID 41209563, 2025). "All samples were positive for FAP reminiscent of the heterogeneous FAP+ CAF-S1 superpopulation from breast cancer." (PMID 41327318, 2025). "For example, αFAP-PE38 inhibited the infiltration of immune cells by depleting FAP+ stromal cells in a breast cancer model, and effectively suppressed tumor growth in vivo when combined with paclitaxel." (PMID 40890855, 2025). "In breast cancer, FAP-positive CAFs mediated Treg activation and exerted immunosuppressive activity in a dipeptidyl peptidase (DPP) 4-dependent manner that was related to a poor outcome." (PMID 40230452, 2025). "The novel PET/CT tracer, [68Ga]-Ga-FAPI, designed for cancer imaging, targets fibroblast activation proteins (FAP) that are overexpressed in various cancer types', inclusive of breast cancer." (PMID 39744055, 2025). "highlighted FAP expression as an independent predictor for extended overall and disease-free survival in breast cancer cases." (PMID 38558814, 2024). "In dogs, overexpression of FAP has already been demonstrated in the stroma of mast cell tumors and mammary carcinomas as well as in the right atrium of beagle dogs with induced atrial fibrillation." (PMID 39188902, 2024). "A series of histopathologic analyses demonstrated strong-to-moderate FAP expression is present in the stroma of breast carcinomas." (PMID 38505595, 2024). "In this work, breast cancer cells transfected to express FAP showed increased growth, adhesion, and migration, even when enzymatic activity was suppressed." (PMID 39765634, 2024). "Patient 6 with breast cancer, characterized by diffuse FAP-positive bone and bone marrow metastases and lymph node metastases in 68Ga-FAP-2286 PET/CT imaging, displayed regression of bone and bone marrow lesions within 10 days." (PMID 38543239, 2024). "Because we confirmed that the growth speed is significantly affected when FAPα-overexpression lines are constructed, especially in breast cancer cells." (PMID 39596363, 2024). "PDPN positivity correlates with greater invasiveness in lung adenocarcinomas and functionally CAFs expressing PDPN and FAP have previously been identified to suppress T cell proliferation in a nitric oxide dependent manner in breast cancer." (PMID 38582812, 2024). "We previously identified 8 clusters of FAP+ CAF (CAF-S1) in breast cancer (BC) by scRNA-seq10, but the origin of this FAP+ CAF heterogeneity in BC is poorly understood." (PMID 38561380, 2024).
breast carcinoma (continued). "In a study of 112 breast cancer patients, abundant stromal FAP expression correlated with significantly longer disease-free and overall survival, contrasting the trends observed in other cancers." (PMID 39035007, 2024). "FAP overexpression has been noted in multiple malignancies, including breast cancer, gastric cancer, and colorectal cancer." (PMID 39511039, 2024). "FAP targeting represents a promising approach to indirectly assess tumor burden as CAFs are the most abundant cells in the breast cancer microenvironment." (PMID 37370912, 2023). "IHC staining demonstrated strong FAP expression in ovarian cancer, breast cancer, and uterine leiomyosarcoma." (PMID 37370912, 2023). "Together, these data provide direct evidence that hybrid cells form in situ in live mammary tumors, have the ability to disseminate, and can be detected in tissue samples of primary breast cancer and metastasis using a combination of pan-CK and FAP markers." (PMID 37607007, 2023). "In conclusion, we provide direct evidence of a hybrid cell population in human breast cancer that can be identified by coexpression of CK and FAP proteins." (PMID 37607007, 2023). "High expression of FAP has been reported in certain human malignancies, including myeloma, breast cancer, lung cancer and gastrointestinal carcinoma." (PMID 37166418, 2023). "For instance, the invasion and migration ability of cancer cells was significantly promoted after coculturing with FAP positive CAFs isolated from the stroma tissue of breast cancer patients." (PMID 37325617, 2023). "In breast cancer for example a subset of Fibroblast Activation Protein (FAP)+ CD29+ CAF designated CAF-S1, have an enhanced capacity to recruit and expand Treg." (PMID 37520560, 2023). "αFAP-PE38 as FAP-targeting immunotoxin presents attractive tumor suppression in breast cancer mouse model." (PMID 36922546, 2023). "In contrast, several other preclinical studies, including mesothelioma, breast cancer, and colon and lung adenocarcinoma, have shown FAP-targeted CAR-T cells control tumor growth or prolonged survival without obvious toxicity." (PMID 37046312, 2023). "Here we established, for the first time, that FAP-α overexpression in triple negative MDA-MB-231 breast cancer cells resulted in significant changes in metabolism." (PMID 36937451, 2023). "In breast cancer, FAP+CAFs are divided into 8 subgroups, among which the TGF-β signalling and extracellular matrix (ECM) -related subgroups are related to primary resistance to immunotherapy." (PMID 37199594, 2023). "According to these data, CAF-mediated EMT through autophagy and overexpression of FAP is critical for invasion and metastasis of breast cancer." (PMID 37461061, 2023). "In breast cancer, FAP+ CAFs particularly the ECM-myCAF and TGFβ-myCAF clusters, increase PD-1 and CTLA-4 expression on the surface of CD4+CD25+FOXP3+ Tregs." (PMID 37166418, 2023). "Results showed that the FAP protein was highly expressed in breast cancer, colon cancer, GBM, HNSC, KIRC, LIHC, LUAD and PAAD." (PMID 37166418, 2023). "Previous findings revealed that FAP was rare to be detected in healthy tissues, notably, FAP had a high expression trend in some kinds of malignant tumors, such as breast cancer, colorectal cancer and pancreatic cancer." (PMID 37325617, 2023). "For example, FAP-targeted PET/CT or PET/MRI has shown diagnostic value in multiple cancers, such as lung cancer, breast cancer, HNSCC and gastric cancer." (PMID 36744260, 2023). "Regarding FAP expression and endothelial cells, we also found significantly positive Spearman correlation coefficients in most tumor entities, e.g., in breast cancer (BRCA), colon adenocarcinoma (COAD), and head and neck cancer (HNSC)." (PMID 36672341, 2023). "In mouse models of colon and breast cancer, it has been shown that killing FAP+ CAFs by CD8+ T lymphocytes prevents primary tumor development and metastasis." (PMID 37007004, 2023).